AXL (AXL receptor tyrosine kinase)
Diseases named in the same sentence as AXL in open-access papers (continued):
Sharing a sentence is not in itself a finding about the gene and the disease.
glioblastoma (continued). "PI3K/AKT pathway could also be regulated via tyrosine kinase AXL, which is the transcriptional target of REV‐ERBβ in glioblastoma cells." (PMID 36066207, 2022). "In addition, TYRO3 and AXL co-immunoprecipitated from cell lysates derived from Rat2 cells with exogenous TYRO3 expression and from a gonadotropin-releasing hormone (GnRH) expressing neuronal cell line, and human glioblastoma and colorectal cancer cell lines expressing endogenous TYRO3 and AXL." (PMID 30501104, 2018). "Furthermore, glioblastoma LN229 cell proliferation is inhibited by Bemcentinib and Gilteritinib in a manner independent of AXL." (PMID 38391974, 2024).
glioma (43 papers, 2009 to 2025). A benign or malignant brain and spinal cord tumor that arises from glial cells (astrocytes, oligodendrocytes, ependymal cells). "For example, an in vitro study showed that long non-coding RNA DNCAR decreased cell apoptosis caused by cisplatin by inducing the signaling of AXL/PI3K/AKT/necrosis factor-kappa B (NF-κB) in glioma cells." (PMID 33876384, 2021). "In contrast to LINC00526, higher expression of AXL was associated with shorter survival time in glioma patients." (PMID 31240814, 2019). "AXL, which is a receptor tyrosine kinase, has been reported to be overexpressed in human glioma and associated with poor prognosis of glioma patients." (PMID 31737660, 2019). "Through searching TCGA data, we found that the expression of AXL was significantly inversely associated with that of LINC00526 in glioma tissues." (PMID 31240814, 2019). "DANCR upregulates the expression of AXL in glioma cells, which in turn activates the phosphatidylinositol-3-kinase (PI3K)/Akt/nuclear factor kappa B (NF-κB) signaling pathway." (PMID 35674307, 2022). "LncRNA DANCR contributes to drug resistance in glioma cells by activating the AXL/PI3K/Akt/NF-κB signaling pathway." (PMID 35674307, 2022). "Based on these results, DANCR promotes cisplatin resistance by activating the AXL/PI3K/Akt/NF-κB signaling pathway in gliomas." (PMID 34065991, 2021). "Patients’ age, KDELC2 expression, IDH1, ATRX, neurofilament, p-AxL, Nur77, H3Lys27, and PDGFRA were associated with glioma patients’ overall prognosis." (PMID 32927743, 2020). "DANCR was known to mediate cisplatin resistance in glioma cells via activating AXL/PI3K/Akt/NF-κB signaling pathway." (PMID 32766131, 2020). "Through competitively binding mR-33a-5P, miR-33b-5P, miR-1-3P, miR-206 and miR-613, ANCR increased AXL expression and activated PI3K/Akt/NF-κB signaling pathway that caused cisplatin resistance in glioma cells." (PMID 31143372, 2019). "Analysis of the TCGA data revealed that the expression of LINC00526 is inversely correlated with that of AXL in glioma tissues." (PMID 31240814, 2019). "Firstly, western blot was applied to examine AXL expression in glioma cells infected with ARL2 overexpression or control vector." (PMID 29843637, 2018). "Mechanistically, ARL2 regulated AXL expression, which was known as an important functional regulator of proliferation and tumorigenicity in glioma cells." (PMID 29843637, 2018). "Altogether, our data suggest that ARL2 serves as an important suppressor for the proliferation, migration and tumorigenicity of glioma cells by regulating the expression of AXL." (PMID 29843637, 2018). "Earlier report and our previous works have described the function of AXL in regulating cell growth, migration and tumorigenesis of glioma." (PMID 29843637, 2018). "Based on these observations, we further investigated the effect of ARL2 expression on AXL in glioma cells." (PMID 29843637, 2018). "Secondly, we found that ARL2 overexpression attenuated the proliferation, clone formation, migration, invasive and tumorigenic capabilities of glioma cells by regulating the expression of receptor tyrosine kinase AXL." (PMID 29843637, 2018). "AXL expression was found in human gliomas with EZH2 expression and is also positively correlated with the grade of malignancy (r2 = 0.391, P = 0.002)." (PMID 23077658, 2012). "AXL has been shown to be involved in tumor invasiveness and metastases in multiple tumors including glioma." (PMID 23077658, 2012). "Knockdown of AXL led to a profound suppression of glioma cell invasiveness in Boyden chamber assays, thus mimicking the phenotype of EZH2 knockdown cells." (PMID 23077658, 2012). "Specific candidates like follistatin and the Gas6/AXL system, point towards future experiments evaluating them in more detail as targets for future therapy of gliomas." (PMID 19558675, 2009). "They indicated that EZH2 triggers glioma invasiveness via transcriptional regulation of AXL." (PMID 34745848, 2021).
glioma (continued). "DANCR via activating AXL/PI3K/Akt/NF-κB signaling pathway could mediate cisplatin resistance in glioma cells." (PMID 34178658, 2021). "Finally, ARL2 overexpression inhibits proliferation, as well as migration and tumorigenicity of glioma cells, through regulation of the receptor tyrosine kinase AXL, a known regulator of glioma tumorigenesis." (PMID 32426352, 2020). "Therefore, LINC00526 and AXL form a double negative feedback loop, which further promotes the down‐regulation of LINC00526 and the up‐regulation of AXL in glioma tissues." (PMID 31240814, 2019). "Next, we investigated whether the tumour suppressive roles of LINC00526 in glioma are dependent on AXL." (PMID 31240814, 2019). "In addition, previous report and our previous study proved that AXL played a critical role in the functional regulation of glioma cells." (PMID 29843637, 2018). "To explore the physiological role of ARL2-AXL axis in glioma cells, we evaluated whether AXL overexpression rescue the phenotype induce by ARL2 overexpression in glioma cells." (PMID 29843637, 2018). "Furthermore, of all included factors, senior glioma patient, PLP2 overexpression, loss of ATRX, and positive expression of AxL, NUR77 or PDGFRA were the independent prognostic factors under cox regression analysis." (PMID 30373180, 2018). "Our study suggests that ARL2 inhibits the proliferation, migration and tumorigenicity of glioma cells by regulating the expression of AXL and may conduct as a new prognostic and therapeutic target for glioma." (PMID 29843637, 2018). "AXL baseline expression was analyzed in the glioma cell line U87MG and the GIC S24 by FACS." (PMID 23077658, 2012). "The N32 glioma was less responsive to the blocking of Gas6 and AXL signaling." (PMID 19558675, 2009). "Besides, lncRNA DANCR could mediate cisplatin resistance in glioma cells via activating the AXL/PI3K/Akt/NF-κB signaling pathway." (PMID 30910838, 2021). "However, recent evidence has shown that Pros1 does bind to and activate AXL in glioma sphere cultures 113, and it modulates AXL expression in oral squamous cell carcinoma cell lines 114, suggesting that Pros1 induces receptor activity function differently in different tumor microenvironments." (PMID 32802188, 2020). "Therefore, LINC00526/EZH2/AXL/PI3K/Akt/NF‐κB form a feedback loop in glioma." (PMID 31240814, 2019). "Finally, AXL expression is found in human gliomas with high EZH2 expression." (PMID 23077658, 2012). "This implies that targeting the Gas6/AXL pathway in gliomas might not only have direct effects on tumor proliferation signals but could have secondary effects by decreasing the vascularization of the tumor and may present a good target for glioma therapy." (PMID 19558675, 2009). "Additionally, they have investigated the theory that AXL signaling stimulates the formation of glioblastoma tumors by immune-suppressive extrinsic signals that alter the tumor microenvironment and internal mechanisms that control the survival and proliferation of glioma stem cells (GSC)." (PMID 38391974, 2024). "The results revealed that older age (≥ 52 years old), high-grade glioma, and high expression of AGTR1, NF1, and AxL were independent prognostic factors." (PMID 37291545, 2023). "By upregulating AXL, DANCR activated the PI3K/Akt/NF-κB signaling pathway in glioma cells, and inhibition of this signaling pathway reversed the effect of DANCR on cisplatin resistance." (PMID 34065991, 2021). "The knockdown of AXL imitated the anti-invasive properties of EZH2 silencing, and AXL secretion was detected in human gliomas with elevated EZH2 secretion." (PMID 34745848, 2021). "Noteworthy, when we compared the tyrosine kinase receptors AXL and MERTK in U87MG cells vs. MDM, AXL was highly expressed only in glioma cells, whilst MERTK was expressed in MDM which denote the difference in the cell type source during heterotypic co-culture." (PMID 34065977, 2021).
glioma (continued). "LINC00526 inhibited glioma cell proliferation, migration and invasion via the LINC00526/EZH2/AXL/NF‐κB/LINC00526 feedback loop." (PMID 31240814, 2019). "In addition, the restoration of AXL by exogenous expression did not fully rescue the defects in U251 glioma cells caused by ARL2 overexpression, which suggested that there might be additional molecular downstream targets associated with ARL2 overexpression." (PMID 29843637, 2018). "Altogether, these results indicated that ARL2 overexpression suppressed the expression of AXL and the activation of ERK in glioma cells." (PMID 29843637, 2018). "We identified several targets involved in glioma growth and migration, specifically CXCL1, CD81, TPT1, Gas6 and AXL proteins." (PMID 19558675, 2009). "Moreover, the concurrent alteration of the FRA1 targets, AXL, CDK6, and FSCN1 correlated with worse prognosis in lung adenocarcinoma, low grade glioma, and clear cell renal cell carcinoma." (PMID 41286309, 2025). "To determine whether radiotherapy affects YAP expression in gliomas, we radiated the glioma cells and found that radiation did not influence the protein level of YAP but increased the protein level of AXL and Cyr61, two target genes of YAP." (PMID 34127812, 2021). "Through upregulating AXL, DANCR activated PI3K/Akt/NF-κB signaling pathway in glioma cells." (PMID 33123287, 2020). "Although a previous study has shown that ARL2 inhibits glioma proliferation and tumorigenicity by downregulating AXL, the functions of other ARL members in glioma remained unknown." (PMID 31234870, 2019). "Collectively, our data identified LINC00526 as a tumour suppressor in glioma via forming a double negative feedback loop with AXL." (PMID 31240814, 2019). "Finally, it was proved in this study that ARL2 regulated AXL expression and activated phospho-ERK in glioma." (PMID 29843637, 2018). "Previous studies have shown that AXL (also known as UFO) and Mer (also known as Nyk) induce EMT and malignant phenotypes in various cancer cells derived from the lung, breast and pancreas, along with glioma and myeloid leukemia." (PMID 29259259, 2017). "Collectively these data suggest that EZH2 drives glioma invasiveness via transcriptional control of AXL independent of histone or DNA methylation." (PMID 23077658, 2012). "This is supported by the fact that treatment with DZNep did not affect AXL expression in glioma cells." (PMID 23077658, 2012). "Collectively, these data indicate that EZH2 controls glioma cell invasiveness via AXL independent of DNA and histone methylation." (PMID 23077658, 2012). "5-aza failed to modulate AXL expression in glioma cells further supporting the notion that EZH2 controls AXL expression in a histone- and DNA methylation-independent fashion." (PMID 23077658, 2012). "What is important, we observed dramatic induction of AXL expression in SH-SY5Y cells by HDAC class I inhibitor, which could be beneficial for the simultaneous repression of AXL and HDAC, as it was described for glioma." (PMID 34944663, 2021).
viral infection (41 papers, 2015 to 2025). "AXL, a member of the TAM (Tyro3, AXL, and Mertk) subfamily of RTKs, is abundantly expressed in lung tissue and has been implicated in viral infections and lung injury." (PMID 41158072, 2025). "Profibrotic macrophages also expressed AXL, a receptor tyrosine kinase that is required for resolution of lung inflammatory disease upon viral infection, induced by GM-CSF, and associated with development of tissue fibrosis in mouse models." (PMID 33622974, 2021). "Interestingly, AXL is associated with viral infection, TLR7/8 transcript abundance, and STAT2 transcript abundance in placenta cells, since their levels vary both when these cells are infected as well as when TLR7/8 or STAT2 are knocked down." (PMID 30453684, 2018). "Since loss of AXL function in DCs protected the cells from viral infection, these results suggested that AXL inhibition might lead to improved antiviral response in infected hosts." (PMID 27350258, 2016). "HUVEC, a widely used primary endothelial cell model for viral infection mechanism, exhibits susceptibility to SFTSV and expresses AXL but lacks DC-SIGN/L-SIGN expression." (PMID 40853130, 2025). "Beyond oncology, AXL also facilitates viral infections, including SARS-CoV-2 and Zika highlighting its importance in both cancer and virology." (PMID 39924521, 2025). "Despite these advancements, the molecular basis of these infectious processes, particularly the functional significance of individual tyrosine residues of AXL in viral infection, remains inadequately explored." (PMID 40853130, 2025). "A comparable response pattern is observed in human tDCs following yellow fever vaccination, a live attenuated virus: circulating tDCs maintain their transcriptional identity postvaccination, including expression of AXL, SIGLEC6, and ADAM33." (PMID 41275417, 2025). "They found that AXL was overexpressed, and that blockade of this receptor decreased viral infection." (PMID 36989308, 2023). "Next, we constructed AXL-knockdown or overexpression cell lines on Jurkat cells and then tested the effect on viral infection." (PMID 35277473, 2022). "Given this, our data provide a mechanistic explanation for previous virology reports showing decreased viral infection in cells treated with AXL inhibitors, and offer a rationale for pharmacological inhibition of AXL in antiviral therapy." (PMID 35622156, 2022). "A more comprehensive understanding of the molecular mechanisms of flavivirus-AXL interaction will provide crucial insights into the virus infection process and the development of anti-flavivirus therapeutics." (PMID 33954117, 2021). "Bemcentinib robustly inhibited virus infection of Vero E6 cells as well as multiple human lung cell lines that expressed AXL." (PMID 34797899, 2021). "Overexpressed AXL in AXL/ACE2 double KO HEK293T cells promote viral infection, reaching levels that are comparable to those of HEK293T cells overexpressing AXL." (PMID 34867819, 2021). "Overexpressing AXL in the double-KO HEK293T cells greatly promoted viral infection, which reached a level similar to that in HEK293T cells overexpressing AXL, indicating that ACE2 is dispensable in AXL-promoted SARS-CoV-2 virus infection." (PMID 33420426, 2021). "The prevalence of this AXL function in distinct viral infections should be carefully considered in the development of pharmacological tools that inhibit this RTK." (PMID 27350258, 2016). "In summary, our studies underscore the function of AXL in calibrating the antiviral versus the immunosuppressive functions of type I IFNs during viral infection." (PMID 27350258, 2016). "Similar studies have also shown that inhibiting AXL and related enzymes can make cells more able to fight off certain types of viral infection." (PMID 27350258, 2016). "One AXL-independent means of viral infection could be the passage of viral RNA during cell division." (PMID 34272257, 2021). "Viral infection was slightly decreased by ACE2/AXL double-KO in HEK293T cells." (PMID 33420426, 2021).
viral infection (continued). "Specifically, the VP1 protein of SV40 could structurally mimic Gas6 to directly interact with AXL to enhance viral infection." (PMID 32172658, 2020). "Furthermore, VP1 protein of the non-enveloped polyomavirus simian virus 40 (SV40) can directly interact with AXL for promoting viral infection." (PMID 32172658, 2020). "However, IP-10, a biomarker for severity of viral infection was enhanced by both pharmacological and genetic inhibition of AXL in astrocytes infected with PRVABC59." (PMID 30735502, 2019). "Thus, our studies highlight the central role of AXL in the protection of the host against viral infections through the tightly regulated production of type I IFNs." (PMID 27350258, 2016). "How does AXL signaling protect the host against viral infection?" (PMID 27350258, 2016). "Given the contrasting immunosuppressive and antiviral functions of type I IFNs, we sought to directly test whether disabling AXL RTK signaling indeed translates into increased resistance to viral infection in vivo." (PMID 27350258, 2016). "To determine whether AXL induction is mediated directly by viral infection or by subsequent cytokine expression, we examined AXL expression in infected, adjacent and mock infected PHHs from the same dataset." (PMID 26313459, 2015). "However, the physiological relevance of AXL on tDCs during viral infection remains unclear and warrants further study." (PMID 41275417, 2025). "Studies have also shown that AXL plays a vital role in various cellular functions, including hematopoiesis, innate immune responses, platelet aggregation, phagocytosis of apoptotic cells, viral infection, vascular integrity, and permeability regulation, and cell survival." (PMID 34438849, 2021). "Taken together, our findings suggest that AXL is a novel candidate receptor for SARS-CoV-2 which may play an important role in promoting viral infection of the human respiratory system and indicate that it is a potential target for future clinical intervention strategies." (PMID 33420426, 2021). "Clinical-grade human recombinant soluble AXL may be useful for blockade of viral infection." (PMID 33420426, 2021). "Thus, our findings suggest that the AXL signaling pathway could play an important role in regulating host responses to these viral infections." (PMID 34439388, 2021). "This discovery sheds light on the intricacies of viral entry and underscores the potential of targeting AXL for therapeutic intervention in SFTSV and possibly other viral infections." (PMID 40853130, 2025). "Of note, ablation of AXL in mice has previously been shown to increase expression of type I IFN while impairing IL-1β production and T cell activation during viral infections." (PMID 39269281, 2024). "We evaluated if PS receptors serve as cell surface receptors for SARS-CoV-2 and found that the PS receptors, AXL, TIM-1 and TIM-4, facilitated virus infection when the SARS-CoV-2 cognate receptor, ACE2, was present." (PMID 34797899, 2021). "After virus infection, the TLR-mediated immune network is stimulated by viral particles, and then, the consequent type I interferon (IFN) antiviral response upregulates AXL expression, which further promotes virus infectivity." (PMID 34497683, 2021). "We evaluated if PS receptors serve as cell surface receptors for SARS-CoV-2 and found that the PS receptors, AXL, TIM-1 and TIM-4, facilitated virus infection when low concentrations of the SARS-CoV-2 cognate receptor, ACE2, was present." (PMID 34159331, 2021). "To confirm that AXL directly induces viral infection independently of its ligand GAS6 or Protein S in serum, we performed control experiments and found that GAS6 and Protein S are dispensable in AXL-induced SARS-CoV-2 virus pseudotype infection." (PMID 33420426, 2021). "We also investigated virus infection of a variety of lung lines that endogenously express TMPRSS2, AXL, and ACE2." (PMID 34797899, 2021).